MMP9 (matrix metallopeptidase 9)
Diseases named in the same sentence as MMP9 in open-access papers (continued):
Sharing a sentence is not in itself a finding about the gene and the disease.
urothelial bladder carcinoma (8 papers, 2006 to 2022). "To further validate the correlations among ATG5/12, Beclin 1, MMP2, and MMP9 in BC, we analyzed urothelial bladder carcinoma datasets on the GEPIA2 web server." (PMID 35449123, 2022). "To further validate the TSP4, MMP2, and MMP9 associations in human BC tumours, we analysed the correlations among TSP4, MMP2 and MMP9 expression in human BC tumours by analysing The Cancer Genome Atlas (TCGA) database for urothelial bladder carcinoma datasets on the GEPIA2 web server." (PMID 34142438, 2021). "We have demonstrated that the overexpression of MMP-9 and higher expression of IL-8 are related to unfavorable prognostic factors of urothelial bladder cancer and tumor recurrence and may be useful in the follow up of the patients." (PMID 22695075, 2012). "In a later study, this same author demonstrated similar behavior of tissue gene expression of MMP-9, TIMP-1, and RECK in patients with urothelial carcinoma of the bladder, with most patients overexpressing MMP-9 underexpressing TIMP -1 and RECK." (PMID 35097136, 2021). "Endostatin, formed by gelatinase B/MMP-9 digestion of the type XVIII collagen α1 chain, blocks VEGFR2 and α5β1-mediated angiogenesis, inhibits gelatinase B/MMP-9 activity and reduces metastasis in patients with high-grade transitional cell carcinoma of the bladder." (PMID 24473089, 2014). "Moreover, the expression level of key EMT-related proteins such as N-Cad, MMP9, Vimentin, Slug and Snail were correspondingly decreased, which indicated us that the up-regulated CDCA3 could participate in the EMT process of bladder urothelial carcinoma." (PMID 33980246, 2021).
adenomyosis (7 papers, 2017 to 2025). The growth of endometrial tissue inside the muscular wall of the uterine corpus. "Our results align with prior studies demonstrating that miR-183 suppresses epithelial cell migration and invasion in adenomyosis by targeting MMP-9." (PMID 41374393, 2025). "On comparing adenomyosis patients with controls, significant differences were observed in the expression of MMP9, MMP11, SERPINA1, IGFBP5, and TIMP1 (p < 0.05); however, MMP7 and THBS1 remained comparable." (PMID 41272701, 2025). "A positive correlation between uterine volume and MMP9 expression in adenomyosis was noticed." (PMID 41272701, 2025). "In addition, tissue from patients with adenomyosis has been shown to have increased expression of matrix metalloproteinase-9 (MMP-9)." (PMID 40340640, 2025). "This indicates that alterations of Nrf2 could trigger changes in the ability of endometrial glands to migrate in adenomyosis, possibly through the regulation of MMP9 expression." (PMID 28817677, 2017). "Further, MMP7, MMP9, and MMP11 appear promising as clinically relevant discriminatory markers of adenomyosis." (PMID 41272701, 2025). "Expression of key genes indicated enhanced ECM remodeling in adenomyosis, with MMP7, MMP9, and MMP11 emerging as potential discriminatory markers." (PMID 41272701, 2025). "Compared with the adenomyosis group, the expression of E-cadherin was increased and the expression of N-cadherin, Twist, Snail, MMP-2, and MMP-9 was decreased in mice of verteporfin group." (PMID 36940085, 2023).
age (7 papers, 2017 to 2025). A temporal measurement of the time period elapsed since an identifiable point in the life cycle of an organism. "Matrix metalloproteinase‐9 (MMP‐9) is associated with several aging and age‐related pathologies." (PMID 40325911, 2025). "In particular, the enrichment of the overexpressed DEG MMP9 in ECM remodeling and tissue degeneration highlights the likely role of ECM remodeling in age-related MMVD." (PMID 38753730, 2024).
age-related macular degeneration (7 papers, 2013 to 2024). Age-related loss of vision in the central portion of the retina (macula), secondary to retinal degeneration. "Interestingly mmp9 is a key marker gene known to be differentially expressed between wet and dry forms of age-related macular degeneration, providing further evidence for a possibly critical role during inflammatory processes." (PMID 39071801, 2024). "In addition to increased ocular levels, the plasma level of MMP-9 was reported to also be increased in age-related maculopathy and CNV patients as well." (PMID 31398819, 2019). "The types and expression levels of MMPs vary by the disease; for example, in age-related macular degeneration, the expression of MMP-2 and MMP-9 is significantly reduced." (PMID 36973823, 2023). "A PubMed search using the terms “age related macular degeneration”, “smoking” and “MMP9” yielded no results." (PMID 36498929, 2022).
airway hyperresponsiveness (7 papers, 2012 to 2024). "MMP2 and MMP9 were also described as essential for inflammatory cell infiltration and induction of airway hyperresponsiveness." (PMID 31842927, 2019). "Seven days following RSV infection, Mmp9-/- mice displayed substantial weight loss, increased RSV-induced airway hyperresponsiveness (AHR) and reduced clearance of RSV from the lungs compared to wild type mice." (PMID 26284919, 2015). "In vitro and in vivo assays also determined that MMP9 significantly reduces RSV replication, host cell viability, airway hyperresponsiveness (AHR), body weight loss and enhances RANTES, IL-1β, SCF and G-CSF production during RSV infection." (PMID 26284919, 2015). "As there is an inverse relationship between MMP-9 and airway hyperresponsiveness, Cordyceps sinensis may reduce leukocyte extravasation and lymphocyte accumulation in the walls of asthmatic airways by the decrease of MMP-9 expression." (PMID 28050193, 2016). "Here we choose to investigate MMP9 as it is linked to several RSV-induced disease manifestations, including airway hyperresponsiveness (AHR) and MMP9 is present at high concentrations in neutrophils, which are the major immune cell present in human BALF from RSV patients." (PMID 26284919, 2015). "Therefore, macrophages from these unstable asthmatics may release more MMP-9, leading to collagen deposition or neovascularization in the basement membrane of airways and contributing to airway hyperresponsiveness." (PMID 31547356, 2019).
cardioembolic stroke (7 papers, 2009 to 2025). "A study published in 2001 firstly showed an association between MMP-9 expression and several subtypes of hemorrhagic transformation after human cardioembolic stroke." (PMID 20514206, 2009). "Additionally, interactions between rs3918242 and rs3787268 in the MMP-9 gene were associated with hemorrhagic transformation in acute ischemic stroke patients with atherothrombosis, small artery disease, and cardioembolic stroke." (PMID 40724896, 2025). "In addition, plasma matrix metalloproteinase-9 (MMP-9) is reported to be associated with the degradation of certain TJs in laboratory studies and has been correlated with the severity of hemorrhagic transformation after cardioembolic stroke." (PMID 33532130, 2021). "Characteristic MMP-9 concentration changes have been also revealed in the course of cardioembolic stroke." (PMID 31701356, 2020). "Demographic and clinical characteristics of patients with cardioembolic stroke used to test miRNAs predicted in silico to affect MMP-9 expression." (PMID 31555200, 2019). "In the current study, we hypothesized that some miRNAs that are related to MMP-9 would be prognostic biomarkers for predicting HT following cardioembolic stroke." (PMID 31555200, 2019). "A three-step approach was adopted to identify whether MMP-9-related miRNAs were prognostic biomarkers for predicting HT following cardioembolic stroke." (PMID 31555200, 2019). "Studies suggest that microRNAs that regulate expression of matrix metalloproteinase (MMP)-9 may be involved in hemorrhagic transformation (HT) after cardioembolic stroke, so we examined whether such microRNAs could predict HT in acute cardioembolic stroke patients." (PMID 31555200, 2019). "Serial MMP-9 and MMP-2 in 39 patients with cardioembolic stroke were determined." (PMID 20514206, 2009).
cerebral malaria (7 papers, 2008 to 2025). A sequestration of Plasmodium falciparum in the brain, which can cause coma and/or seizures. "In vivo, mice with cerebral malaria (CM) display high levels of both MMP-9 and TIMP-1, and in human patients TIMP-1 serum levels directly correlate with disease severity." (PMID 23967215, 2013). "MMP-9 expression is higher in mice brain with cerebral malaria and human monocytes fed with Hz or trophozoite-parasitized red blood cells displayed increased activity and protein/mRNA expression of MMP-9 and increased production of TNF." (PMID 20642847, 2010). "Tissue inhibitor of metalloproteinases 1 is the most upregulated protein in cerebral malaria, which along with elevated MMP8 and MMP9 transcription, underscores the importance of the metalloproteinase pathway in central nervous system pathophysiology." (PMID 40383794, 2025). "More recently, it has been shown that human monocytes fed with Hz or IRBC display increased MMP-9 activity and protein/mRNA expression and increased production of TNF and a role of MMP-9 and TNF in the onset of cerebral malaria has been postulated." (PMID 20642847, 2010). "Similarly, in cerebral malaria, MMP-2 and MMP-9 were overexpressed as soon as 8 days p.i., with evidences of MMP-9 activation." (PMID 28814754, 2017).
chronic myeloid leukemia (7 papers, 2014 to 2024). "In contrast, PIWIL1 expression downregulates MMP-2 and MMP-9 and inhibits the proliferation and migration ability of chronic myeloid leukemia cells." (PMID 31443431, 2019). "The EO from the leaves of Pinus roxburghii induced apoptosis along with inhibition of NF-κB and inhibited the expression of genes associated to cell survival (survivin, c-FLIP, Bcl-2, Bcl-xL, c-Myc, c-IAP2), proliferation (cyclin D1), and metastasis (MMP-9) in KBM-5 (chronic myeloid leukemia) cells." (PMID 30441836, 2018). "HAND2‐AS1 restoration resulted in reduced N‐cadherin, vimentin, MMP‐2 and MMP‐9 expression, which was consistent with a former study in which HAND2‐AS1 reduced MMP‐2 and MMP‐9 expressions in chronic myeloid leukaemia." (PMID 32314545, 2020). "Gelatinase B/MMP-9 degrades ICAM-1, down-regulating leukocyte homing and promotes evasion of the immune system by chronic myeloid leukemia cells by solubilizing cell membrane ICAM-1." (PMID 24473089, 2014). "Additionally, XN regulates the anti-angiogenic effects of NF-κB by suppressing the level of MMP-9, VEGF, and ICAM-1 stimulated by TNF in chronic myelogenous leukemia." (PMID 38611849, 2024).
chronic pancreatitis (7 papers, 2005 to 2023). A chronic inflammatory process causing damage and fibrosis of the pancreatic parenchyma. "In addition, in SAP, MMP-9 has been identified as an early marker of pancreatic necrosis, and possibly a susceptibility factor for chronic pancreatitis." (PMID 35157709, 2022). "In the course of acute and chronic pancreatitis, the expression of MMP-9 is increased as a result of the intra-acinar conversion of trypsinogen to trypsin, causing the activation of MMP−9." (PMID 36830471, 2023). "Consistent with previous work, analysis of the expression levels of several genes in both ductal carcinomas and chronic pancreatitis showed elevated levels of the matrix-remodeling gene MMP-9." (PMID 23737761, 2013). "Serum MMP-9 levels were significantly higher in PDAC (255.14 ng/ml) than those in chronic pancreatitis (210.22 ng/ml, p = 0.009) and healthy control (203.77 ng/ml, p = 0.027)." (PMID 18706098, 2008). "In addition, we assessed the activation of PSCs by determining the levels of Col1a1, Mmp9, and Il6 factors previously shown to be upregulated in PSCs during chronic pancreatitis." (PMID 36835366, 2023). "Indeed, there was a 10-fold increase in MMP-9 gene expression in ductal carcinomas compared with samples from patients diagnosed with chronic pancreatitis." (PMID 23737761, 2013). "Therefore, we measured serum levels of MMP-9 in PDAC, and found that serum MMP-9 had a higher level in PDAC than in chronic pancreatitis and healthy controls." (PMID 18706098, 2008).
cutaneous melanoma (7 papers, 2015 to 2023). A primary melanoma arising from atypical melanocytes in the skin. "In addition, it has been validated that MMP2 and MMP9 are implicated in the development and metastasis of cutaneous melanoma." (PMID 29108247, 2017). "Our correlation analysis of the transcriptomic data of 368 cutaneous melanoma samples revealed a positive correlation of PD-L1 to IFN-γ, STAT-1, IFN-γ driven CXCL10 and CXCL9 as well as to acidosis driven MMP9." (PMID 38102680, 2023). "The aim of the study was to define clinical utility of serum biomarkers: VEGF, MMP-2, MMP-9, TIMP-1, and YKL-40 in patients with skin melanoma at locoregional stage." (PMID 26002577, 2015). "In the presented study, we have evaluated a clinical utility of the concentrations of VEGF, MMP-2, MMP-9, TIMP-1, and YKL-40 in serum of patients with skin melanoma at locoregional disease." (PMID 26002577, 2015).
diffuse large B-cell lymphoma (7 papers, 2007 to 2026). "The current work tracked immunohistochemistry marker CD4, CD8, CD68, and MMP9 staining in diffuse large B cell lymphoma cases." (PMID 35083113, 2022). "About 50% of the diffuse large B-cell lymphomas (DLBCL) expressed MMP9." (PMID 18093334, 2007). "Finally, certain lymphoproliferative diseases are also associated with expression of COL6A1, COL18A1, MMP3 and TIMP1, and a subset of patients with diffuse large B cell lymphoma and adverse prognosis show decreased expression of POSTN, SPARC, COL1A1, COL3A1,CSTK, MMP9 and LAMB3." (PMID 33379263, 2020). "Similarly, in case of patients with diffuse large B-cell lymphoma treated with modern chemotherapy with or without CD20 antibody, MMP-9 and TIMP-1 seem to have lost their prognostic value." (PMID 25190551, 2015).
encephalitis (7 papers, 2019 to 2025). An acute inflammatory process affecting the brain parenchyma. "In JE in mice, MMP9 is vividly upregulated intrathecally simultaneously with the development of the histopathological features of encephalitis, accompanied by MMP2 and MMP7." (PMID 40003967, 2025). "A high MMP-9/TIMP1 ratio in pediatric patients is closely tied to encephalitis and prolonged febrile seizures." (PMID 37365625, 2023). "MMP9 −/− mice have a reduced severity of encephalitis with a better-preserved BBB function." (PMID 40003967, 2025). "Matrix metalloproteinase-9 (MMP-9) can mediate BBB destruction triggered by the West Nile virus, thereby leading to severe encephalitis." (PMID 41012511, 2025). "Especially MMP9, MMP8 and MMP3 are vividly upregulated intrathecally in murine encephalitis models, with a potential redundancy of their proteolytic effects." (PMID 40003967, 2025). "Since disruption of the BBB is a poor prognostic factor of anti-NMDAR encephalitis, the measurement of CD44 and MMP9 in CSF and serum can be used as a potential biomarker to indicate its prognosis in the clinical arrangement." (PMID 37481571, 2023). "For the serum MMP9 expression level, a positive correlation was demonstrated between the serum MMP9 expression level and the Qalb in anti-NMADR encephalitis patients (r = 0.493, p = 0.007)." (PMID 37481571, 2023). "The level of serum MMP9 was related to Qalb, a common clinical indicator to evaluate the destruction of the BBB, in anti-NAMDR encephalitis patients." (PMID 37481571, 2023). "The patients with encephalitis had the most significantly increased levels of MMPs in CSF, and MMP-3, MMP-8, and MMP-12 were exclusively increased in this group, whereas MMP-9 in CSF was increased in the patients with VZV meningitis." (PMID 30777092, 2019). "A similar positive correlation was shown between the CSF sTREM2 expression level and the CSF CD44 (r = 0.702, p < 0.0001) and between the CSF sTREM2 expression level and the serum MMP9 expression levels (r = 0.428, p = 0.021) in the anti-NMDAR encephalitis patients." (PMID 37481571, 2023). "MMP9 concentration increases in WNV-infected mice in vivo in the order paralleling the progression of the disease: in serum simultaneously with viremia, in brain microvasculature before encephalitis onset and in the brain parenchyma in parallel with the progress of encephalitis." (PMID 40003967, 2025).
Encephalopathy (7 papers, 2016 to 2026). Encephalopathy is a term that means brain disease, damage, or malfunction. "This study aimed to investigate the cellular mechanisms of PRV-induced encephalopathy and the role of matrix metalloproteinase-9 (MMP-9) in blood–brain barrier (BBB) disruption." (PMID 40176142, 2025). "Moreover, recent study revealed that the neuro-inflammation altered BBB permeability via upregulation of MMP-9 in acute hypobaric hypoxia related encephalopathy model." (PMID 39556255, 2024). "Therefore, an increased MMP-9/TIMP-1 ratio has been suggested to impair the BBB, which ultimately leads to encephalopathy." (PMID 36670630, 2022). "In addition, the levels of MMP-9 and TIMP-1 are upregulated in premature infants with BPD and encephalopathy, which has been previously confirmed." (PMID 33263620, 2020). "The authors suggested that MMP-9 level and MMP9/TIMP1 ratio might indicate central nervous system damage and development of encephalopathy." (PMID 28104930, 2016).
enteritis (7 papers, 2018 to 2023). Inflammation of the small intestine. "As the MMP-8/TIMP-1 and MMP-9/TIMP-1 ratios were concerned in enteritis patients, significant differences between acute and convalescent samples were detected except for MMP-9/TIMP-1 ratio for Salmonella patients." (PMID 30551610, 2018). "In subsequent studies, we will further explore the specific effects of AEE on the gut flora of rats with enteritis, further validate its function in vivo, and explore the relationship between AEE and MMP-9 in more depth." (PMID 38139262, 2023). "MMP9 is a unique MMP, which was highly expressed in inflammation, especially in the samples of enteritis and bowel cancer tissues." (PMID 36362252, 2022). "Expression of some of the previously identified enteropathy markers was however regulated opposite to what would be expected during enteritis in AB1h or A22h (Ig mu chain C, Hes-1, Cebpz), or was also affected in the R23h line (IGKV4-1, MMP-9)." (PMID 30063731, 2018). "TAC, MMP-9 and MMP-2 estimations may be noteworthy in lamb enteritis diagnosis and monitoring of its therapeutic programs wherein TAC is the best among them." (PMID 34395600, 2021).
gallbladder cancer (7 papers, 2012 to 2025). "NK-1R antagonist, L703606, could also attenuate the expression of metastasis-related factors like MMP9 in gallbladder cancer cells." (PMID 36177059, 2022). "In gallbladder carcinoma GBC-SD cells, lupeol was shown to induce apoptosis and inhibit invasion by downregulating the activity of p-EGFR and MMP-9." (PMID 32571387, 2020). "However, a study has linked the expression of prohibitinin with the expression of MMP9 and ERK signaling in gallbladder cancer." (PMID 41179704, 2025).